PRC1 (protein regulator of cytokinesis 1)
Diseases named in the same sentence as PRC1 in open-access papers (continued):
Sharing a sentence is not in itself a finding about the gene and the disease.
neurodevelopmental disorder (4 papers, 2020 to 2022). A behavioral and cognitive disorder with onset during the developmental period that involves impaired or aberrant development of intellectual, motor, or social functions. "Despite possessing counteracting functions, mutations in PRC1 and PR-DUB give rise to phenotypically related neurodevelopmental disorders, suggesting that an ‘optimal’ level of H2AK119ub1 is required for healthy brain development." (PMID 36547251, 2022). "Disruption of PRC1 and PR-DUB lead to neurodevelopmental disorders (NDDs) associated with both localised and/or systemic growth abnormalities." (PMID 36547251, 2022). "Mutations in PRC1 members such as PHC1 and PCGF2 lead to human neurodevelopmental disorders." (PMID 36117635, 2022). "In this review, we will focus on advancements regarding the composition and opposing molecular functions of mammalian PRC1 and PR-DUB, and explore how their dysfunction contributes to the emergence of neurodevelopmental disorders." (PMID 36547251, 2022). "As PRC1 and PR-DUB hold opposing functions to control H2AK119ub1 levels across the genome, it is plausible that such neurodevelopmental disorders arise through a common mechanism." (PMID 36547251, 2022).
cardiovascular disease (2 papers, 2022 to 2023). "Recent evidence suggests that H2Aub and its ubiquitinating enzyme PRC1 are responsible for the onset and progression of cardiovascular disorders." (PMID 38114486, 2023). "Although researchers are primarily investigating the relationship between H2Aub and tumors, the role of PRC1 in regulating H2Aub levels in chromatin and the involvement of transcriptional targets in cardiovascular disorders, specifically MI/RI, is yet to be determined." (PMID 38114486, 2023). "However, the mechanisms underlying PRC1-regulated H2Aub suppression of target genes are not well understood in the context of cardiovascular disease." (PMID 38114486, 2023).
adenocarcinoma (1 paper, 2017). A common cancer characterized by the presence of malignant glandular cells. "422, 95%CI = 1.183–3.273, P = 0.031), p-TNM Stage (HR = 1.752, 95% CI = 1.312–2.437, P = 0.042) and high expression of PRC1 protein (HR = 2.391, 95% CI = 1.528–2.908, P = 0.024) were independent prognostic factors for adenocarcinoma patients." (PMID 28646916, 2017).
blood cancer (1 paper, 2023). "These cell lines were chosen mainly due to the association of PRC1 with the hematopoiesis process in blood cancers." (PMID 36737841, 2023).
cardiac diseases (1 paper, 2021). "This may provide some new insights into the pathology of cardiac diseases caused by PRC1 loss-of-function." (PMID 34768802, 2021).
PRC1 also shares sentences with these, for which no sentence is quoted: bacterial infection (2 papers); childhood cancer (2); lung diseases (2); adenocarcinoma of the colon (1); adenoma (1); amyotrophic lateral sclerosis (1); Brugada syndrome (1); chondroblastoma (1); colitis (1); Cornelia de Lange syndrome (1); embryonic carcinoma (1); epithelial dysplasia (1); gonadotroph adenomas (1); Hepatitis (1); idiopathic pulmonary fibrosis (1); ischemia (1); Joubert syndrome 31 (1); latent infections (1); leiomyoma (1); liver cirrhosis (1); Malignant Brain Tumor (1); mesenchymal tumors (1); mesothelioma (1); multiple myeloma (1); myelodysplastic syndrome (1); myocardial infarction (1); nasal polyps (1); neurodegenerative disease (1); neuroendocrine tumor (1); oculofaciocardiodental syndrome (1).
A further 11 diseases each share a sentence with PRC1 in 1 paper.